FOXM1 (forkhead box M1)
Diseases named in the same sentence as FOXM1 in open-access papers (continued):
Sharing a sentence is not in itself a finding about the gene and the disease.
ovarian carcinoma (continued). "To explore the correlation between OTUB1 and FOXM1 in ovarian cancer, we analyzed the immunostaining of OTUB1 and FOXM1 protein in samples from 200 ovarian cancer patients." (PMID 27167337, 2016). "OTUB1 and FOXM1 expression were consistently correlated in immunoblotting results of total protein extracted from 25 ovarian carcinoma tissue samples (r=0.448, p=0.025)." (PMID 27167337, 2016). "Our results indicate that OTUB1 exerts oncogenic activities in ovarian cancer and its expression is tightly correlated with FOXM1 in human ovarian cancer samples." (PMID 27167337, 2016). "In this study, we characterized the critical role of transcription factor Forkhead box protein M1 (FOXM1) in aerobic glycolysis of human epithelial ovarian cancer (EOC) and its molecular mechanisms." (PMID 27351131, 2016). "Overexpression of FOXM1 and its potential correlations to worse prognosis and/or drug-resistance in epithelial ovarian cancer (EOC) have been reported by several labs." (PMID 26299613, 2015). "Overexpression of FOXM1 increased cisplatin-resistance and sphere formation in cisplatin-sensitive and low FOXM1-expressing ovarian cancer cells." (PMID 25537512, 2015). "FOXM1 is frequently upregulated in ovarian cancers, most notably (and significantly) in high-grade tumors with aggressive behavior, such as metastasized lymph nodes." (PMID 25537512, 2015). "Beyond its role in cell cycle progression, FOXM1 has been shown to contribute to other important oncogenic phenotypes in ovarian cancer, including platinum and taxane resistance, epithelial-to-mesenchymal transition (EMT), cell migration, and cell invasion." (PMID 26243836, 2015). "We discover that EXO1 is a potential downstream gene of FOXM1 in ovarian cancer, FOXM1 directly binds to EXO1 promoter and enhances EXO1 expression." (PMID 24824601, 2014). "We show that FOXM1 is up-regulated in chemoresistant ovarian cancer compared to chemosensitive ovarian cancer." (PMID 24824601, 2014). "To further determine the expression pattern of FOXM1 in ovarian cancer cells, we treated A2780 and SKOV3 with different concentrations of cisplatin, and discovered the mRNA level of FOXM1 increased only slightly after cisplatin treatment." (PMID 24824601, 2014). "Multivariate analysis confirmed FOXM1 expression as an independent prognostic factor for ovarian cancer." (PMID 25411964, 2014). "Our findings help to define FOXM1 as a potential prognostic marker as well as a therapeutic target in ovarian cancer." (PMID 25411964, 2014). "Correlations between FOXM1 and clinicopathologic parameters have been reported in ovarian cancer, but the results were inconsistent." (PMID 24885308, 2014). "The aim of this study was to evaluate the role of FOXM1 in ovarian cancer tumorigenesis and paclitaxel resistance." (PMID 25411964, 2014). "In this study, we aimed to investigate the potential role of FOXM1 in ovarian cancers with chemoresistance to cisplatin." (PMID 24824601, 2014). "Effects of FOXM1 knockdown on ovarian cancer cell migration, invasion and mitotic catastrophe were also studied." (PMID 25411964, 2014). "In conclusion, overexpression of FOXM1 was found to be correlated with poor patients' survival and to paclitaxel-mediated mitotic catastrophe in ovarian cancer cells." (PMID 25411964, 2014).
ovarian carcinoma (continued). "In conclusion, we found that FOXM1 directly regulated EXO1 expression to promote the DNA repair pathway upon cisplatin treatment, and demonstrated that FOXM1 knockdown can enhance sensitivity of ovarian cancer cells to cisplatin." (PMID 24824601, 2014). "Our results indicate that FOXM1 is upregulated in chemoresistant ovarian cancer samples, and defends ovarian cancer cells against cytotoxicity of cisplatin." (PMID 24824601, 2014). "In Vitro Transwell assays were employed to study the effects of transient silencing of FOXM1 on ovarian cancer cell motility and invasion." (PMID 25411964, 2014). "Collectively, these results indicate that targeting FOXM1 provides a strategy for sensitizing ovarian cancer to cisplatin." (PMID 24824601, 2014). "The purpose of this study was to examine the expression levels of FOXM1 in epithelial ovarian cancer (EOC), to identify the relationship between FOXM1 expression and patient survival, and to investigate the role of FOXM1 in human ovarian cancer development." (PMID 24885308, 2014). "FOXM1 should be further investigated as a potential prognostic marker and therapeutic target for ovarian cancer." (PMID 25411964, 2014). "The effects of FOXM1 expression on cancer cell migration, invasion and paclitaxel resistance were also studied in an attempt to evaluate FOXM1 as a potential molecular prognostic marker and therapeutic target for ovarian cancer." (PMID 25411964, 2014). "Our studies therefore uncover that the FOXM1/EXO1 axis protects ovarian cancer cells after cisplatin treatment by enhancing the DNA damage repair pathway." (PMID 24824601, 2014). "To assess the FOXM1 expression levels, we compared the levels of FOXM1 expression in normal ovarian tissues, ovarian cancer tissues and ovarian cancer cell lines by real-time PCR and western blot analyses." (PMID 24885308, 2014). "In the majority of cases, ovarian cancer cells showed both a cytoplasmic and nuclear staining for FOXM1, but staining was restricted to cytoplasm or nuclear in a few cases." (PMID 24885308, 2014). "In this study, we show that high nuclear FOXM1 expression is significantly correlated with stage, shorter overall survival and disease-free survival of ovarian cancer patients." (PMID 25411964, 2014). "Consistent with previous reports in other cancer cell lines, thiostrepton downregulates FoxM1 expression in several ovarian cancer cell lines as well as in endometrial (HEC-1A) and lung (NCI-H23) cancer cell lines." (PMID 25426548, 2014). "FOXM1 facilitates DNA repair through regulating direct transcriptional target EXO1 to protect ovarian cancer cells from cisplatin-mediated apoptosis." (PMID 24824601, 2014). "In summary, our study demonstrated that casticin-induced dephosphorylation of FOXO3a regulates the expression of FoxM1 and its target genes, including survivin, PLK1 and p27KIP1, and this causes apoptosis in ovarian cancer cells." (PMID 23761826, 2013). "In the present study, we investigated the possibility that casticin induces apoptotic cell death and aimed to determine the role of FoxM1 in casticin-dependent ovarian cancer cell apoptosis." (PMID 23761826, 2013). "A small inhibitory RNA (siRNA) knockout of FoxM1 potentiated casticin-induced apoptosis in ovarian cancer cells." (PMID 23761826, 2013). "In a more detailed follow-up study, in vitro models based on the ovarian cancer cell line OVCA433 showed a clear dependency of FOXM1 on upstream activation of MEK/ERK signaling." (PMID 23528888, 2013). "Our results suggest that FoxM1 is a target of casticin in ovarian cancer cells, as FoxM1 is known to induce oncogenesis and its downregulation causes the inhibition of cell growth." (PMID 23761826, 2013). "In this study, we present evidence that GRB7, ERK phosphorylation and FOXM1 are increased in ovarian cancer." (PMID 23285101, 2012). "Recently, FoxM1 signaling was described as essential for coordinating cell cycle progression and DNA repair in ovarian cancer." (PMID 23110199, 2012).
ovarian carcinoma (continued). "Collectively, these findings confer that GRB7 positively upregulates ERK activity which in turn elevates FOXM1 in ovarian cancer cells." (PMID 23285101, 2012). "Taken together, these data indicate there is a close interplay among GRB7, ERK activity and FOXM1 in regulating ovarian cancer oncogenesis particularly in high-grade tumor." (PMID 23285101, 2012). "Our results emphasize the importance of the GRB7/ERK/FOXM1 pathway in tumorigenic properties and argue this pathway for a promising therapeutic target in high-grade ovarian cancer." (PMID 23285101, 2012). "In this study, by using IHC analysis of ovarian cancer tissue array, we show that GRB7, ERK phosphorylation and FOXM1 are concomitantly increased in ovarian cancer samples." (PMID 23285101, 2012). "Intriguingly, the expressions of GRB7 (P<0.0001), ERK phosphorylation (P<0.001) and FOXM1 (P<0.001) showed a significant stepwise increase pattern along Grade 1 to Grade 3 ovarian cancers." (PMID 23285101, 2012). "Functionally, inhibiting ERK activity by U0126 or PD98059 and FOXM1 expression by Thiostrepton remarkably inhibit ovarian cancer cell migration/invasion and tumor growth in vitro and in vivo." (PMID 23285101, 2012). "In this study, we show that the expressions of GRB7, ERK and FOXM1 were significantly correlated with the progression of ovarian cancer." (PMID 23285101, 2012). "All in all, these findings indicate that GRB7, ERK phosphorylation and FOXM1 form an oncogenic convergence in high-grade ovarian cancer pathogenesis." (PMID 23285101, 2012). "We have previously reported that GRB7, ERK phosphorylation and FOXM1 are overexpressed in ovarian cancer samples particularly in high-grade tumors." (PMID 23285101, 2012). "Clinico-pathological analysis of GRB7, ERK phosphorylation and FOXM1 expressions in ovarian cancer tissue array (OVC1021)." (PMID 23285101, 2012). "In summary, this study shows that aberrant activation of GRB7/ERK/FOXM1 signaling cascade is significantly correlated with the development of ovarian cancer." (PMID 23285101, 2012). "Here, we characterized the role of ERK/FOXM1 signaling in mediating the metastatic potential of ovarian cancer cells." (PMID 21858223, 2011). "Taken together, these data suggest that FOXM1 significantly regulates cell proliferation and cell migration/invasion in ovarian cancer cells." (PMID 21858223, 2011). "Here, we showed that both mRNA and protein levels of FOXM1 were up-regulated in ovarian cancer tissues and cell lines." (PMID 21858223, 2011). "For the cell lines study, the expressions of pERK and FOXM1 also demonstrated a good correlation in a panel of ovarian cancer and HOSEs cell lines." (PMID 21858223, 2011). "In conclusion, our study revealed a link between ERK/FOXM1 signaling axis and the metastatic behavior of ovarian cancer cells." (PMID 21858223, 2011). "Immunohistochemical (IHC), immunoblotting and semi-quantitative RT-PCR analyses found that both phospho-ERK and FOXM1 were frequently upregulated in ovarian cancers." (PMID 21858223, 2011). "In this study, we have showed that FOXM1 was aberrantly up-regulated in ovarian cancer, particularly in high-grade sub-type." (PMID 21858223, 2011). "Taken together, these findings support an essential role of FOXM1 in mediating the effect of ERK on cell migration in ovarian cancer cells." (PMID 21858223, 2011). "In this study, we firstly analyzed the expression status and clinicopathological correlation of FOXM1 in ovarian cancer." (PMID 21858223, 2011). "Nevertheless, all of these observations suggest that the aberrant up-regulation of FOXM1 attributes the tumorigenic properties in high-grade ovarian cancer." (PMID 21858223, 2011).
ovarian carcinoma (continued). "Concordant weak to very strong staining of pERK and FOXM1 were also observed from borderline cystademoma to Grade 3 tumor, implicating the importance of the two proteins in tumor progression of ovarian cancer." (PMID 21858223, 2011). "Intriguingly, we found that pERK and FOXM1 levels were tightly correlated during cancer progression, especially in high-grade ovarian cancer." (PMID 21858223, 2011). "Taken together, we believe that up-regulated ERK activity and the subsequent increase of FOXM1 expression contribute further induction of oncogenic behaviors, supporting that ERK/FOXM1 signaling axis facilitates cell migration in ovarian cancer." (PMID 21858223, 2011). "Many of the genes from this set that are highly expressed in CEPI promote entry into and progression through the cell cycle (e.g., FOXM1, PTTG1, AURKA) and have been previously associated with stage III epithelial ovarian cancers." (PMID 20040092, 2009). "After miR-370 inhibition, FoxM1 expression could not be silenced; lncRNA-PVT1 can directly bind to and stabilize the FoxM1 protein, both of which promote the malignant progression of ovarian cancer." (PMID 40486884, 2025). "Moreover, GSEA revealed the suppression of FOXM1_pathway and AURORA_B_pathway as common pathways in both the STL001-treated and FOXM1-KD ovarian cancer cells." (PMID 38697979, 2024). "Moreover, exosomes from AMSCs were able to promote ovarian cancer cell growth and motility in vitro and metastasis formation in mouse models by regulating the levels of the forkhead box protein M1 (FOXM1) protein." (PMID 39697630, 2024). "Since domatinostat reduced the expression of FOXM1 in ovarian cancer cells, we surmised that survivin may be involved in domatinostat-induced apoptosis of ovarian cancer cells." (PMID 37445993, 2023). "Our results clearly showed that domatinostat inhibited the expression of FOXM1 in ovarian cancer cells at clinically relevant concentrations and accordingly reduced their viability and enhanced the growth inhibitory effects of standard ovarian cancer chemotherapeutic agents cisplatin and paclitaxel." (PMID 37445993, 2023). "Knockdown experiments showed survivin expression was dependent on FOXM1 in ovarian cancer cells." (PMID 37445993, 2023). "First of all, we asked whether domatinostat could inhibit the expression of FOXM1 in ovarian cancer as it did in other cancer types." (PMID 37445993, 2023). "Our results thus suggest that domatinostat, as an inhibitor of FOXM1 expression, may become an attractive and viable treatment option for ovarian cancer." (PMID 37445993, 2023). "Importantly, we were able to confirm that FOXM1 knockdown led to reduced viability of ovarian cancer cells, just." (PMID 37445993, 2023). "Yet, it was found to promote ovarian cancer progression by regulating the mRNA processing of FOXM1." (PMID 36977668, 2023). "We then examined the expression levels of survivin after FOXM1 knockdown and observed reduced expression of survivin upon silencing of FOXM1, which demonstrated that survivin expression was dependent on FOXM1 in ovarian cancer cells." (PMID 37445993, 2023). "In summary, we have shown in this study that domatinostat, at clinically relevant concentrations, reduces the expression of FOXM1 and its transcriptional target survivin, and accordingly the viability of ovarian cancer cells alone and in combination with chemotherapeutic agents." (PMID 37445993, 2023). "We next confirmed whether the reduced survivin expression in ovarian cancer cells after domatinostat treatment was attributable to its inhibition of FOXM1 expression." (PMID 37445993, 2023). "Mounting evidence suggests that FOXM1 overexpression contributes to chemoresistance in ovarian cancer, while it has been well established that survivin confers chemoresistance on cancer cells in general by increasing the threshold for chemotherapy-induced apoptosis." (PMID 37445993, 2023).
ovarian carcinoma (continued). "To understand the mechanism by which HO-ADSC exosomes increased proliferation, migration, and invasion in ovarian cancer cell lines, we focused on FOXM1, as previous investigations have shown that the FOXM1 pathway is commonly activated in various solid cancers." (PMID 36359787, 2022). "Similarly, a recent report also unveiled that circ-FOXM1 serves as a ceRNA of FOXM1 to modulate paclitaxel resistance of ovarian cancer cells." (PMID 35799265, 2022). "In addition, we demonstrated that HO-ADSC exosomes promote the growth and metastasis of ovarian cancer cells via a mechanism dependent on the FOXM1, Cyclin F KIF20A, and MAPK signaling pathways." (PMID 36359787, 2022). "Our study provides a lead compound of FOXM1 inhibitor which might be as a potential targeted probe for ovarian cancer treatment." (PMID 35680842, 2022). "DZY-4 showed the highest affinity towards FOXM1, and its inhibitory effect on proliferation and migration of ovarian cancer at the cellular level was better than or equal to that of cisplatin, while its efficacy was equivalent to that of cisplatin in a nude mouse model." (PMID 36505747, 2022). "Moreover, our data support that Cyclin F and KIF20A are involved in FOXM1-mediated ovarian cancer formation and development, and high Cyclin F and KIF20A expression was associated with poor prognosis in patients with ovarian cancer." (PMID 36359787, 2022). "The Cancer Genome Atlas (TCGA) revealed that the FOXM1 transcriptional pathway was eccentrically activated in over 85% of high-grade serous carcinoma (HGSC) cases and that high FOXM1 expression was associated with the stage and prognosis of ovarian cancer." (PMID 36505747, 2022). "Our laboratory also demonstrated that Cyclin F and KIF20A are involved in FOXM1-mediated ovarian cancer cell proliferation and metastasis, and high expression of Cyclin Fand KIF20A was associated with poor prognosis in patients with ovarian cancer." (PMID 36359787, 2022). "Although many downstream genes driven by FOXM1 have been elucidated, most of the downstream targets of FOXM1 in ovarian cancer remain unclear." (PMID 36359787, 2022). "Our study provides a lead compound of FOXM1 inhibitor which may serve as a potential targeted therapy agent for ovarian cancer." (PMID 35680842, 2022). "In summary, DZY-4 shows potential as a therapeutic agent for ovarian cancer and may be used as a drug lead for further studies and as a biochemical research tool to promote studies investigating FOXM1 as a drug target." (PMID 36505747, 2022). "FOXM1 is commonly elevated and its high level predicts a worse prognosis for ovarian cancer." (PMID 35680842, 2022). "In conclusion, FOXM1 plays an important role in the development of ovarian cancer as well as in drug resistance in this disease, indicating that inhibition of FOXM1 activity may play a role in ovarian cancer therapy." (PMID 36505747, 2022). "Moreover, JQ1 also demonstrated anti-tumor effects via inhibiting the expression of Forkhead box protein M1 (FoxM1) in ovarian cancer and aurora A kinase in triple-negative breast cancer, respectively." (PMID 36187481, 2022). "Overexpression of miR-370 could lead to the inhibition of ovarian cancer by suppressing FOXM1 at the posttranscriptional level." (PMID 35069793, 2022). "Furthermore, cisplatin-resistant ovarian cancer tissues and cells display increased FOXM1, which therefore acts as an independent indicator of the rapid progression of platinum-resistant epithelial ovarian cancer (EOC);." (PMID 36505747, 2022). "Accordingly, knockdown of FOXM1 or its downstream targets increases the sensitivity to standard chemotherapy in many human cancers, including colorectal, gastric, lung, ovarian cancer, retinoblastoma, and nasopharyngeal carcinoma." (PMID 34262016, 2021).